SMARCD2 (SWI/SNF related BAF chromatin remodeling complex subunit D2)
Description:
Involved in transcriptional activation and repression of select genes by chromatin remodeling (alteration of DNA-nucleosome topology). Component of SWI/SNF chromatin remodeling complexes that carry out key enzymatic activities, changing chromatin structure by altering DNA-histone contacts within a nucleosome in an ATP-dependent manner. Critical regulator of myeloid differentiation, controlling granulocytopoiesis and the expression of genes involved in neutrophil granule formation.
Synonyms: BAF60B; PRO2451; Rsc6p; CRACD2; SGD2
Tractability: PROTAC: UniProt records ubiquitination sites on it; ubiquitination databases record sites on it; its protein half-life has been measured.
Gene: Protein-coding gene on chromosome 17 (63,832,081 to 63,843,065, reverse strand). Ensembl gene ENSG00000108604.
Subcellular location: Nucleus
Subcellular location (Human Protein Atlas): Nucleoplasm
Pathways (Reactome):
Chromatin organization: Formation of neuronal progenitor and neuronal BAF (npBAF and nBAF); Formation of the embryonic stem cell BAF (esBAF) complex; Formation of the non-canonical BAF (ncBAF) complex; Formation of the polybromo-BAF (pBAF) complex; RMTs methylate histone arginines
Gene expression (Transcription): RUNX1 interacts with co-factors whose precise effect on RUNX1 targets is not known; Regulation of endogenous retroelements by Piwi-interacting RNAs (piRNAs)
Developmental Biology: Regulation of MITF-M-dependent genes involved in pigmentation
Gene Ontology:
Molecular function: ATP-dependent chromatin remodeler activity; nucleosomal DNA binding; protein binding; transcription coactivator activity; transcription coregulator activity
Biological process: chromatin remodeling; positive regulation of cell differentiation; positive regulation of double-strand break repair; positive regulation of myoblast differentiation; positive regulation of T cell differentiation; regulation of G0 to G1 transition; regulation of G1/S transition of mitotic cell cycle; regulation of mitotic metaphase/anaphase transition; regulation of nucleotide-excision repair; regulation of transcription by RNA polymerase II; nucleosome disassembly; positive regulation of DNA-templated transcription
Cellular component: chromatin; nucleoplasm; protein-containing complex; SWI/SNF complex; bBAF complex; brahma complex; kinetochore; nuclear matrix; RSC-type complex; nucleus
Genetic constraint (gnomAD): Loss-of-function variants: 39 observed, 66.89 expected, observed/expected ratio (o/e) 0.58, 90% interval 0.45 to 0.76. The upper end of that interval is the gene's LOEUF score, 0.76, which puts it in group 3 of 6, group 1 being the genes least tolerant of losing a copy. Missense variants: 537 observed, 671.07 expected, observed/expected ratio (o/e) 0.8, 90% interval 0.75 to 0.86. Synonymous variants: 249 observed, 256.52 expected, observed/expected ratio (o/e) 0.97, 90% interval 0.87 to 1.08.
Homologues: Orthologues: chimpanzee SMARCD2 (99% identical), dog SMARCD2 (99% identical), rabbit SMARCD2 (99% identical), mouse Smarcd2 (98% identical), pig SMARCD2 (98% identical), rat Smarcd2 (98% identical), guinea pig SMARCD2 (91% identical), macaque SMARCD2 (89% identical), tropical clawed frog smarcd2 (73% identical), zebrafish smarcd2 (72% identical), Caenorhabditis elegans ham-3 (42% identical), Caenorhabditis elegans swsn-2.2 (41% identical), and 3 more. Paralogues in human: SMARCD1 (64% identical), SMARCD3 (63% identical).
Diseases named in the same sentence as SMARCD2 in open-access papers:
SMARCD2 is named in the same sentence as 25 diseases in open-access papers, as found by Europe PMC text mining. Sharing a sentence is not in itself a finding about the gene and the disease. The quoted sentences say what the papers report.
breast carcinoma (2 papers, 2023 to 2025). "While SMARCD2 is known to play a crucial role in regulating chromatin accessibility and is amplified in many patients, evidence regarding its role in breast cancer remains scarce and needs further exploration." (PMID 41278204, 2025). "SMARCD2, BCL7C and SS18L1 are amplified in 6%–8% of breast cancer patients from the TCGA and METABRIC breast cancer patient cohorts." (PMID 41278204, 2025). "SMARCD2 protein expression assessed with IHC was not prognostic in the examined breast cancer cohort." (PMID 37445737, 2023).
leukaemia (2 papers, 2015 to 2023). "In order to assess the effect of SWI/SNF complex subunits Smarca4, Smarcd2 or Dpf2 depletion in leukaemia, we transduced MLL-AF9 transformed mouse spleen cells with viruses expressing shRNA target sequences against the genes of each subunit." (PMID 26571505, 2015). "Moreover, chromatin accessibility profiling of leukemia cells disrupted for cBAF (Smarcd2 knockout), MLL1 (Kmt2a knockout) or MLL4 (Kmt2d knockout) showed that these chromatin factors are required to maintain optimal accessibility at the Stat5a and Runx2 binding loci." (PMID 37580596, 2023). "In contrast, LOF of cBAF (Smarcd2 and Smarcb1 knockouts), MLL4-COMPASS (Kmt2d knockout) and Prmt1 pushed leukemia toward basophil and erythroid fates." (PMID 37580596, 2023). "Here we further explore the role of SMARCA4 and the two SWI/SNF subunits SMARCD2/BAF60B and DPF2/BAF45D in leukaemia." (PMID 26571505, 2015). "To assess the relevance of our observations in a physiological context, we transplanted sublethally-irradiated mice with MLL-AF9 cells transduced with shRNAs targeting either Smarca4, Smarcd2, Dpf2, or non-targeting control (shScr) and monitored mice for the onset of leukaemia." (PMID 26571505, 2015).
neutropenia (2 papers, 2022 to 2023). A decrease in the number of neutrophils found in the blood. "Recently, bi-allelic SMARCD2 mutations have been reported in five children, causing autosomal recessive congenital neutropenia with specific granulocytes deficiency (CN-SGD); a syndrome resulting in G-CSF resistant neutropenia, recurrent infections, and dysplastic myelopoiesis." (PMID 36135322, 2022).
breast tumors (1 paper, 2021). "Analyses of human breast tumors indicate that SOX4 mRNA is uniformly overexpressed in basal-like tumors relative to adjacent normal tissue along with the SWI/SNF catalytic subunit SMARCA4 and SMARCB1 SMARCC1, SMARCD2, and ACTL6A, which encode for the essential subunits of this complex." (PMID 33837205, 2021).
liver fibrosis (1 paper, 2022). "Interestingly, the CC genotype of rs2727324 (SMARCD2, TCAM1P) was associated with depletion of Bacteroides dorei and Marinifilaceae, which we previously reported as depleted in subjects with liver fibrosis in the CCHC." (PMID 36386790, 2022).
lung adenocarcinoma (1 paper, 2021). A carcinoma that arises from the lung and is characterized by the presence of malignant glandular epithelial cells. "For this, we made use of a GR activity score (explained above) and the lung adenocarcinoma dataset from TCGA (91/877 tumours harboured SWI/SNF mutations; SMARCB1 18.09%; SMARCC2 9.52%, SMARCD2 6.66%, SMARCD3 1.90%, ARID1A 29.52%, ARID2 31.42%, SMARCE1 2.85%)." (PMID 34272384, 2021).
melanoma (1 paper, 2022). A malignant, usually aggressive tumor composed of atypical, neoplastic melanocytes. "The genes encoding these subunits are mutated at low frequency in melanoma, with SMARCD3 being slightly more frequently altered then the SMARCD1 and SMARCD2 genes." (PMID 35323214, 2022). "Because of their demonstrated interactions with MITF, it will be important to conduct more extensive functional studies of both SMARCD1 and SMARCD2 during melanocyte development and in melanoma." (PMID 35323214, 2022). "SMARCD1 and SMARCD2 both interact with MITF and may have important roles in melanocyte development and melanoma." (PMID 35323214, 2022). "SMARCD1 and SMARCD2 also co-immunoprecitated with MITF in melanoma cells; however, the role these paralogues play in regulating melanoma tumorigenicity is not known." (PMID 35323214, 2022).
osteosarcoma (1 paper, 2025). A usually aggressive malignant bone-forming mesenchymal neoplasm, predominantly affecting adolescents and young adults. "Indeed, overexpression of the SMARCD2 SWIFT domain in U2OS osteosarcoma and ES2 ovarian cancer cell lines significantly attenuated proliferation." (PMID 40766474, 2025).
Sézary syndrome (1 paper, 2023). "Other SWI/SNF genes recurrently altered in CTCLs are SMARCE1 and SMARCD2 (each amplified in 20% Sézary syndrome patients, N = 25), ARID2 (deleted in 8% Sézary syndrome patients, N = 25), and SMARCB1 (point mutation frequency ~ 3%, combined N = 433)." (PMID 36810086, 2023).
tumor (9 papers, 2017 to 2025). "Whole exome sequencing revealed missense mutations in the DNA-repair and chromatin-remodeling genes FANCM and SMARCD2, and a tumor-derived cell line revealed a complex karyotype suggesting chromosomal instability." (PMID 34041014, 2021). "For instance, the knockdown of Smarcc1, Smarcd1, or Smarcd2 impaired the survival of mouse AML cells, confirming their tumor-maintaining role in this tumor type." (PMID 36810086, 2023). "Similarly, the lncRNA LINC01133 may regulate the activity of tumor suppressor pathways by dysregulating ACTL6A, SMARCD2, SMO, PHC3, and CENPP." (PMID 34925461, 2021).
cancer (2 papers, 2021 to 2025). A tumor composed of atypical neoplastic, often pleomorphic cells that invade other tissues. "Finally, as MOLM-13 cells are dependent on PU.1 for proliferative maintenance, we sought to determine the impact of SMARCD2 loss and the ability of either WT SMARCD2 or mutant R290W SMARCD2 to rescue cancer cell line proliferation in culture." (PMID 40766474, 2025). "Together, these data substantiate our biochemical results by demonstrating that the SMARCD2 SWIFT domain is necessary for recruitment of mSWI/SNF by PU.1 in cells and the subsequent activity at PU.1 target genes necessary to uphold cancer cell proliferation." (PMID 40766474, 2025).
prostate (1 paper, 2022). "Similarly to SMARCD1, we found that numerous downstream targets of SMARCD2 (e.g., PTGR1, TRMP8, PGC) and SMARCD3 (e.g., EGF, PIK3AP1, HSD3B1) were AR-driven genes that are involved in prostate tumorigenesis, progression and metastasis." (PMID 36611918, 2022).
SMARCD2 also shares sentences with these, for which no sentence is quoted: acute myeloid leukemia (1 paper); Alpha-thalassemia (1); congenital neutropenia (1); diabetes (1); hepatocellular carcinoma (1); medulloblastoma (1); mental retardation (1); Myelodysplasia (1); neuroblastoma (1); ovarian carcinoma (1); sarcoma (1); specific granule deficiency (1); T-cell acute leukemia (1).